CXCR4 (C-X-C motif chemokine receptor 4)
Diseases named in the same sentence as CXCR4 in open-access papers (continued):
Sharing a sentence is not in itself a finding about the gene and the disease.
breast carcinoma (continued). "Because the TGF-β/SMAD3 signaling can upregulate CXCR4 expression in breast cancer, promoting metastasis, and its ligand CXCL12 is enriched in the bone marrow microenvironment, we evaluated whether SOST silencing could change in the expression of these factors in SCP2 cells." (PMID 36581888, 2022). "However, HER2 was shown to promote the CXCL12/CXCR4/AKT axis only in breast cancer." (PMID 34064589, 2021). "A meta-analysis of the results of 15 studies (3104 patients in total) found that the expression of CXCR4 in breast cancer tissues was significantly higher than that in adjacent tissues, and high expression of CXCR4 in whole cells or the cytoplasm often indicated poor prognosis of breast cancer." (PMID 34198652, 2021). "With these preliminary results, we can further study the specific signal pathways and mechanisms that affect TNBC after CXCR4 knockout and the mechanism of inhibition of breast cancer progress after single knockout, which may provide a new target for the treatment of breast cancer." (PMID 35111484, 2021). "In addition, knockdown CXCR4 expression in breast cancer cells decreases tumor growth rate in mice." (PMID 34503103, 2021). "In other breast cancer studies with dense chemotherapy with GSCMF, it is believed that dose-dense treatment may partly reflect the inhibition of micrometastasis homing and/or paracrine survival associated with CXCR4." (PMID 33773539, 2021). "Finally, findings demonstrating different phosphorylation patterns of LASP1 in breast cancer and chronic myeloid leukemia may have implications for CXCR4 function and tyrosine kinase inhibitor treatment." (PMID 32075106, 2020). "Moreover, detrimental actions of ACKR3/CXCR4 dimers have been described in breast cancer." (PMID 33096815, 2020). "Moreover, other computational approaches such as information theory that has recently been applied in the field of biological signal transduction could be beneficial to study the role of the CXCL12/CXCR4 pathway in breast cancer pathogenesis." (PMID 33096815, 2020). "Notably, BCSCs have high CXCR4 expression and are defined as a pro-metastatic subpopulation, whereas the expression of CXCL12 defines regions with a higher risk of causing metastasis for breast cancer invasion." (PMID 32751846, 2020). "Increasing evidence suggested that CXCR4 could be regarded as a putative CSCs marker in various malignancies, including glioma, non-small cell lung cancer, prostate cancer, renal cell carcinoma, and breast cancer." (PMID 32232002, 2020). "However, at the same concentration, tubeimoside-1 attenuated CXCR4 expression in breast cancer, thus inhibiting CXCL12-induced cell invasion and metastasis; the anti-metastasis effect might offer cancer patients better chances at long-term survival." (PMID 33552000, 2020). "In addition, CXCR4 effects in breast cancer depend on the disease subtype." (PMID 33096815, 2020). "Similar to previous research, forced CXCL12/CXCR4 signaling in metastatic breast cancers promoted immune system evasion, making it a potential target for inhibiting the resistance of therapeutics to immune checkpoint blockades in metastatic breast cancers patients." (PMID 31815619, 2019). "Therefore, we hypothesized that the relationship between AGTR1 and CXCR4/SDF-1α has a great influence on lymph node metastasis in breast cancer." (PMID 31219799, 2019). "Further areas of interest for CXCR4-directed imaging might include HER2-positive breast cancers." (PMID 30191351, 2018). "We then proceeded to exploit the apoptotic kinship between Nef M1 and CXCR4 to suppress the growth and metastasis of primary colorectal tumors in mice and recently found that M1 exhibits profound anti-proliferative activity against various CXCR4-expressing breast carcinomas." (PMID 29682200, 2018). "Therefore, down-regulation of CXCR4 in triple negative metastatic breast cancer cells could greatly decrease their metastatic potential." (PMID 30564115, 2018).
breast carcinoma (continued). "Indeed, in breast cancer patients it was reported that low serum CXCL12 levels may favor the migration of tumor cells overexpressing CXCR4, predicting and promoting the development of distant metastases." (PMID 30012106, 2018). "Previous findings have identified estrogen as a positive regulator of the CXCL12/SDF‐1 gene in breast cancer cells, and we have described that such regulation is part of a positive autocrine feedback loop involving CXCR4 and estrogen receptors to promote cell growth." (PMID 30051594, 2018). "Interestingly, a recent study using a mouse model of breast cancer showed that TAMs are recruited via CCR2 signaling to primary tumors where they induce CXCR4 expression in response to tumor-derived TGFβ and then migrate toward the blood vessel via CXCL12 to promote intravasation of cancer cells." (PMID 30483271, 2018). "Encouraged by the significant inhibitory effects of E5 on the CXCR4/CXCL12 axis, in this work, we applied E5 to breast cancer cells and mouse models to investigate whether E5 could sensitize breast cancer cells to chemotherapeutics and to reveal its underlying mechanisms." (PMID 29263923, 2017). "Therefore, novel drugs capable of decreasing the CXCR4 level may be a potential therapy for breast cancer treatment." (PMID 28446538, 2017). "NT21MP inhibited tumor growth and the expression of PDGFRα, and EMT-associated proteins had similar expression patterns to the experimental results observed in vitro, suggesting NT21MP may inhibit tumor resistance by inhibiting the CXCR4/PDGFRα signaling mechanism in breast cancer." (PMID 28415580, 2017). "Furthermore, I3C could induce inhibition on breast cancer bone metastasis by inhibiting CXCR4 and MMP-9 expression through downregulation of the NF-κB signaling pathway." (PMID 28698459, 2017). "Thus, targeting CXCR4 to inhibit the PDGFRα signaling pathway with an appropriate therapeutic agent may represent a means of controlling the breast cancer progression." (PMID 28415580, 2017). "Moreover, it was showed that breast cancer cells overexpressing CXCR4 metastasize to distant sites, where SDF-1 is highly expressed, raising the possibility that targeted therapies against SDF-1/CXCR4 axis may inhibit tumor growth, as described in vitro." (PMID 29285291, 2017). "These authors acknowledge that GRK3 likely regulates other GPCRs that have relevance to cancer; in agreement with their speculation, the data presented herein describe an important functional role for GRK3 in regulating CXCR4 that impacts metastatic breast cancer progression." (PMID 27049755, 2016). "Based on observed data, we suggest, that CXCR4 antagonist could affect mobilization and trafficking of CTCs as well as self-renewal capacity of cancer cells and thus could represent promising drugs in breast cancer." (PMID 26896000, 2016). "Therefore, novel drugs capable of downregulating the CXCR4 axis may demonstrate potential for breast cancer treatment." (PMID 27556298, 2016). "Finally, we have demonstrated the inhibitory effects of activated PPARγ on CXCR4 expression and migratory abilities also in CAFs as an additional mechanism that may impact breast cancer progression." (PMID 27556298, 2016). "However, despite these studies, either the regulatory mechanism by which PPARγ may regulate CXCR4 expression in breast cancer cells or how PPARγ works in the context of breast tumor microenvironment remain largely unknown." (PMID 27556298, 2016). "CXCR4, a member of the cell surface G-protein-coupled, seven-span transmembrane receptor family, is overexpressed in more than 20 types of human tumors, including breast cancer, prostate cancer, colorectal cancer, melanoma, neuroblastoma, and renal cell carcinoma." (PMID 27175473, 2016). "Therefore, drugs able to inhibit CXCR4 activation may add critical tools to reduce tumor progression, especially in the most aggressive form of the breast cancer disease." (PMID 27556298, 2016).
breast carcinoma (continued). "In addition to TNBC, CXCR4 overexpression also occurs in other breast cancer subtypes." (PMID 26848769, 2016). "In our resected mouse mammary tumors, the CXCR4:GRK3 expression ratio was stable even after 6 weeks of tumor implantation and distant metastasis, suggesting that the CXCR4:GRK3 ratio is preserved and could be a useful prognostic indicator at extended times during the disease course." (PMID 27049755, 2016). "Hence, higher CXCR4 expression in cancer specimens might predict a worse outcome in patients with basal-like breast cancer subtype." (PMID 26161302, 2015). "Induction of certain ligands in cancer cells as they progress may also determine the chemokine receptor required for the macrophage accumulation since the primary tumors developed by mouse breast cancer cells that overexpress CXCL12 or CX3CL1 recruit macrophages through CXCR4 or CX3CR1 respectively." (PMID 26275794, 2015). "Thus, understanding how CXCR4 expression is regulated in breast cancer cells could suggest approaches to decrease bone metastasis of breast tumor cells." (PMID 25773070, 2015). "Therefore, CXCR4 is being considered a prognostic marker in breast cancer." (PMID 26161302, 2015). "Moreover, by comparing the nucleic acids into exosomes from plasma of breast cancer patients divided by poor and good prognostic, several stemness and metastatic-related mRNAs in exosomes were identified, which were also increased in CXCR4-exosomes." (PMID 26528758, 2015). "In addition, we used a xenograft mouse model established by intracardiac injection of tumor cells to show that ANGPTL2 knockdown in breast cancer cells attenuates tumor cell responsiveness to CXCL12 by decreasing CXCR4 expression in those cells, thereby decreasing bone metastasis." (PMID 25773070, 2015). "Furthermore, the CXCR4/CXCL12 axis could mediate the chemotaxis of cancer stem cells that are involved in the metastasis of breast cancer stem cells and cancer cell survival and proliferation." (PMID 24475985, 2014). "Together, our mechanistic in vitro assays and in vivo results suggest that a reduction in chemokine CXCL12 expression, with an enhancement of CXCR4 expression, provoked by COUP-TFI, could be associated with an increase in the invasive potential of breast cancer cells." (PMID 24906407, 2014). "In addition, paracrine signal loops between TAMS and tumor-aiding fibroblasts that secrete CXCL12 to CXCR4 over-expressing breast cancer cells increase the effectiveness of epidermal growth factor (EGF) gradients significantly increasing the occurrence of metastasis." (PMID 25385001, 2014). "Consequently, we hypothesize that the CXCR4/PI3K/AKT/MMP-9 signaling pathway is involved in the bone metastasis of breast cancer." (PMID 24959222, 2014). "In addition miR-218 may facilitate MDA-MB-231 breast cancer bone metastasis by up-regulating CXCR4, a chemokine receptor supporting breast cancer cell migration to bone and mediating tumor growth in bone." (PMID 25019555, 2014). "Although CXCR4 is expressed in a wide range of tissues, its expression is low or absent in normal tissues and becomes important in malignant cells of many human cancers types, including breast cancer, ovarian cancer, melanoma, prostate cancer and colorectal cancer." (PMID 24629239, 2014). "Hence, CXCR4+ cells could contribute to the development of therapeutic resistance and relapse in breast cancer." (PMID 24475985, 2014). "However, the clinical application of CXCR4 for breast cancer prognosis is still very limited." (PMID 24475985, 2014). "We infer that in the case of breast cancer, a CXCR4 inhibitor could improve survival and prognosis." (PMID 24475985, 2014). "Furthermore, the CXCR4/PI3K/AKT/MMP-9 pathway may be important in the bone metastasis of breast cancer." (PMID 24959222, 2014). "Hence, CXCR4 antagonists could have a significant therapeutic impact on primary and metastatic breast cancer by disrupting tumor vasculature in the microenvironment." (PMID 24475985, 2014).
breast carcinoma (continued). "In addition, as CXCR4 is involved in the motility and chemotaxis of breast cancer cells, the suppression of CXCR4 expression may significantly reduce the migration of breast cancer cells to distant organs." (PMID 24959222, 2014). "Moreover, the enhanced expression of CXCR4 in breast cancer cells can also play critical roles for their preferential metastatic spread to distant sites, including bones and lungs, which secrete high levels of SDF-1 ligand molecules that act as a chemoattractant gradient." (PMID 23301832, 2013). "Since we found both PDGFR and CXCR4 overexpression in association with SHH MB, and it has been shown that PDGF-D overexpression induces CXCR4 and promotes metastasis in breast cancer cells, we postulated that there may be a functional relationship between PDGFR and CXCR4." (PMID 23497290, 2013). "Therefore, we speculated that PKCζ may be involved in HGF-induced CXCR4 expression in breast cancer, and may affect the behaviors of migration and invasion in breast cancer cells." (PMID 22242160, 2012). "Thus, understanding the mechanisms and molecular pathways that affect CXCR4 expression and cellular signaling might have important implications for breast cancer cell metastasis." (PMID 22242160, 2012). "In this study, we investigated the role of CXCR4/CXCL12 in breast cancer cell migration and adhesion with a focus on its dependence on liver ECM components that may provide an organ-specific microenvironment for rapid tumour cell extravasation into this major metastatic organ." (PMID 22253872, 2012). "Down-regulated expressions of c-erbB-2 and CXCR4 may be a novel mechanism of chemotherapy; the changes of these objective markers may be useful in evaluating the clinical response of neo-adjuvant chemotherapy in breast cancer." (PMID 23046610, 2012). "Samples with high expression of CXCR4, particularly local high expression of CXCR4, often had extensive lymph node metastasis, indicating that CXCR4 may play pro-metastatic roles in the lymphatic metastasis of breast cancer." (PMID 23181100, 2012). "Thus, research in this field may be relevant to better understand the biology of feline mammary tumour, also as a comparative model for human breast cancer, and to evaluate the CXCR4 role in cancer mechanisms." (PMID 22417013, 2012). "Moreover, immunohistochemistry screening of feline mammary tumours may have interesting applications in clinical practice as prognostic factor and to evaluate the possible response to CXCR4 inhibitors." (PMID 22417013, 2012). "Furthermore, our signaling studies in breast cancer cell lines as well as in tumors derived from experimental mice have revealed that synthetic cannabinoids inhibit tumorigenesis by suppressing the phosphorylation of CXCR4 and its downstream target, ERK." (PMID 21915267, 2011). "Also, the role of CXCR7 in breast cancer cell motility, tumor growth and metastasis is still unclear, with the effect of coexpression of CXCR4 and CXCR7 in these processes mostly unknown." (PMID 22152016, 2011). "This study investigated a series of matched primary and lymph node metastasis breast cancer tumors to demonstrate whether the expression of the CXCR4 and CCR7 chemokine receptors, along with expression of EGFR, predicts increased risk of metastasis and mortality." (PMID 20181250, 2010). "The relationship between Nrp2 expression and lymph node metastasis, VEGF-C expression, CXCR4 expression, and other established clinicopathological variables (these data were cited in our previous papers), including prognosis, was analyzed in human breast cancer." (PMID 19580679, 2009). "In addition, cytoplasmic CXCR4 expression may serve as a significant prognostic factor for long-term survival in breast cancer." (PMID 19025611, 2008). "Furthermore, cytoplasmic CXCR4 expression may serve as a significant prognostic factor for long-term survival in breast cancer." (PMID 19025611, 2008).
breast carcinoma (continued). "Therefore, SDF-1, together with its receptor CXCR4, may have potential value when assessing long-term clinical outcome in breast cancer." (PMID 15987445, 2005). "In addition, the CXCR4 promoter displayed a significantly lower mean relative luciferase activity in the human liver tissue slices (0.18%) than in the primary breast cancer samples (37.7%) or breast cancer tissue slices (36.0%)." (PMID 16457694, 2005). "In the present study, therefore, we compare five candidate promoters (for Cox-2, EGP-2, SLPI, survivin and CXCR4) for specific transcriptional control in breast cancer, which might hold promise in the context of future gene therapy or virotherapy regimes for this disease." (PMID 16457694, 2005). "In contrast, since the expression of MEG3 is lost or significantly reduced in breast cancer cells, CTCF is recruited to the promoter/enhancer region of CXCR4 to promote the transcription." (PMID 40548301, 2025). "In breast cancer, iCAFs promote T‐cell exclusion by secreting CXCL12, which binds to CXCR4 on T cells." (PMID 41164803, 2025). "For example, the CXCR4 receptor, primarily activated by CXCL12, can be used to direct nanoparticles specifically to cancers expressing CXCR4, such as ESCA, breast cancer and ovarian cancer." (PMID 40134607, 2025). "In breast cancer metastasis, particularly in Triple Negative Breast Cancer (TNBC), LIM, and SH3 Protein 1 (LASP1) interacts with AGO2 in a C-X-C Motif Chemokine Receptor 4 (CXCR4)-dependent manner." (PMID 40863728, 2025). "In CXCR4-positive cancers, such as breast cancer, the CXCL12/CXCR4 axis drives metastasis to organs rich in CXCL12, including the lungs, bone marrow, and lymph nodes." (PMID 40282969, 2025). "In this study, we have highlighted the significance of TGFβ-1, IL19, CXCR4, BMP1, IL1A, VCAN, PDK1, and WNT2 in breast cancer pathology." (PMID 41348904, 2025). "Altogether, these results indicated that CXCR4 was the major target downstream MEG3 and MEG3 regulated breast cancer cell migration via CXCR4." (PMID 40548301, 2025). "Using these two strategies, we assessed the therapeutic activity of anti-PD1 in combination with AMD3100, a small molecule antagonizing CXCR4, and anti-IL6 neutralizing antibodies, on immunotherapy-resistant triple negative 4T1 breast cancer." (PMID 40822347, 2025). "We compared the TGFβ-1, CXCR4, IL19, BMP1, VCAN, and WNT2 expression in different subtypes of breast cancer, and the results demonstrated that BMP1, and WNT2 were consistently overexpressed in HER-2 subtype." (PMID 41348904, 2025). "In HER-2-positive breast cancer, HER-2 signaling upregulates CXCR4 expression while simultaneously inhibiting its degradation, a mechanism that contributes to enhanced invasive potential." (PMID 40607416, 2025). "A variety of CXCR4 antagonists, such as LY2510924, POL5551, AMD3100, and AMD3465, have been developed and applied in breast cancer research." (PMID 40890855, 2025). "The chemokine receptor CXCR4 and its ligand CXCL12 play a significant role in breast cancer cell colonization in bone." (PMID 39980332, 2025). "These systems achieved significant prolongation of survival in mouse models of breast cancer and AML by combining the blockade of CXCR4 signalling with the targeted delivery of encapsulated doxorubicin." (PMID 40307933, 2025). "For example, the CXCR4 inhibitor AMD3100 can mobilize HSCs, and inhibition of CXCR4/ CXCL12 signaling has been shown to be useful as an adjuvant in the treatment of hematological malignancies (e.g., leukemia) and solid tumors (e.g., breast cancer)." (PMID 40979214, 2025). "In the liver, dormant breast cancer cells are likely reactivated by liver‐specific pericytes secreting CXCL12, which induces CXCR4‐mediated NK cell quiescence and promotes CXCR4‐dependent outgrowth of dormant cancer cells." (PMID 41020040, 2025).